JAG1 (jagged canonical Notch ligand 1)
Description:
Ligand for multiple Notch receptors and involved in the mediation of Notch signaling. May be involved in cell-fate decisions during hematopoiesis. Seems to be involved in early and late stages of mammalian cardiovascular development. Inhibits myoblast differentiation (By similarity). Enhances fibroblast growth factor-induced angiogenesis (in vitro).
Synonyms: hJ1; CD339; JAGL1; AHD; AWS; AGS; AGS1; CMT2HH; DCHE
Tractability: Small molecule: a structure with a bound ligand is known. Antibody: UniProt places it where antibodies can reach, with high confidence; its Gene Ontology location is reachable by antibodies, with high confidence; UniProt predicts a signal peptide or a membrane-spanning region; the Human Protein Atlas places it where antibodies can reach. PROTAC: ubiquitination databases record sites on it.
Gene: Protein-coding gene on chromosome 20 (10,637,684 to 10,674,396, reverse strand). Ensembl gene ENSG00000101384.
Subcellular location: Membrane; Cell membrane
Subcellular location (Human Protein Atlas): Golgi apparatus; Plasma membrane
Pathways (Reactome):
Signal Transduction: Activated NOTCH1 Transmits Signal to the Nucleus; NOTCH2 Activation and Transmission of Signal to the Nucleus; NOTCH3 Activation and Transmission of Signal to the Nucleus; NOTCH4 Activation and Transmission of Signal to the Nucleus; RAC1 GTPase cycle; RAC3 GTPase cycle
Disease: Constitutive Signaling by NOTCH1 HD Domain Mutants; Constitutive Signaling by NOTCH1 HD+PEST Domain Mutants; Constitutive Signaling by NOTCH1 PEST Domain Mutants; Constitutive Signaling by NOTCH1 t(7;9)(NOTCH1:M1580_K2555) Translocation Mutant
Developmental Biology: Nephron development
Gene expression (Transcription): RUNX3 regulates NOTCH signaling
Gene Ontology:
Molecular function: molecular adaptor activity; Notch binding; phospholipid binding; protein binding; growth factor activity; structural molecule activity; calcium ion binding
Biological process: negative regulation of cell migration; negative regulation of cell-cell adhesion; negative regulation of cell-matrix adhesion; negative regulation of stem cell differentiation; neuronal stem cell population maintenance; Notch signaling pathway; positive regulation of transcription by RNA polymerase II; pulmonary artery morphogenesis; pulmonary valve morphogenesis; T cell mediated immunity; angiogenesis; aorta morphogenesis; aortic valve morphogenesis; cardiac neural crest cell development involved in outflow tract morphogenesis; cardiac right ventricle morphogenesis; cardiac septum morphogenesis; cell fate determination; endocardial cushion cell development; endothelial cell differentiation; hemopoiesis; keratinocyte differentiation; myoblast differentiation; nephron development; nervous system development; podocyte development; and 13 more
Cellular component: membrane; plasma membrane; adherens junction; apical plasma membrane; extracellular region; apical part of cell
Genetic constraint (gnomAD): Loss-of-function variants: 19 observed, 131.93 expected, observed/expected ratio (o/e) 0.14, 90% interval 0.099 to 0.21. The upper end of that interval is the gene's LOEUF score, 0.21, which puts it in group 1 of 6, group 1 being the genes least tolerant of losing a copy. Missense variants: 1,006 observed, 1,583.2 expected, observed/expected ratio (o/e) 0.64, 90% interval 0.6 to 0.67. Synonymous variants: 544 observed, 595.3 expected, observed/expected ratio (o/e) 0.91, 90% interval 0.85 to 0.98.
Homologues: Orthologues: macaque JAG1 (99% identical), chimpanzee JAG1 (99% identical), rabbit JAG1 (99% identical), guinea pig JAG1 (98% identical), dog JAG1 (97% identical), pig JAG1 (97% identical), mouse Jag1 (97% identical), rat Jag1 (97% identical), tropical clawed frog jag1 (84% identical), Caenorhabditis elegans F55H12.3 (30% identical), Drosophila melanogaster Ser (23% identical), Drosophila melanogaster Delta (19% identical), and 2 more. Paralogues in human: JAG2 (54% identical), NOTCH4 (29% identical), DLL1 (21% identical), DLL4 (20% identical), DNER (14% identical).
Diseases named in the same sentence as JAG1 in open-access papers:
JAG1 is named in the same sentence as 350 diseases in open-access papers, as found by Europe PMC text mining. Sharing a sentence is not in itself a finding about the gene and the disease. The quoted sentences say what the papers report.
breast carcinoma (185 papers, 2009 to 2025). "Lapatinib-mediated HER2 inhibition in HER2+ breast cancer cells upregulated JAG1 expression associated with enrichment of cancer stem cells." (PMID 39890784, 2025). "Upregulation of JAG1 and FAT2 has furthermore been linked to poor prognosis in breast cancer, and a Jagged-1/Notch2/PDGFR stroma–epithelial mechanism has been described in a poor prognosis fibroblast subset." (PMID 38172915, 2024). "Kaplan–Meier analysis showed that higher expression of each of MYC and JAG1 is associated with shorter breast cancer patient relapse-free survival, underlining their oncogenic roles in human breast cancer." (PMID 38886396, 2024). "JAG1 has shown to be associated with poor overall survival in women with advanced breast cancer and disease recurrence." (PMID 36476410, 2022). "In the breast epithelium primary tumor, hypoxia induces the loss of some epithelial characteristics via Jagged1(JAG1)/Notch activation in the breast cancer stem cells (BCSCs)." (PMID 36605720, 2022). "High expression of Notch1 and Jag1 is associated with poor overall survival (OS) in breast cancer, suggesting the importance of this signaling axis in human breast cancer." (PMID 34911937, 2021). "Clinical studies have revealed an association between high-level expression of NOTCH1 and JAG1 in breast cancer and poor prognosis." (PMID 34374886, 2021). "Larger studies have shown that expression of Notch1/4 and JAG1 is associated with poor prognosis in breast cancer." (PMID 30515368, 2018). "Earlier studies in breast cancer reported that high expression levels of Notch1 and Jag1 were associated with poor prognosis, suggesting a possible interplay between estrogen and the Notch signaling pathway." (PMID 29996493, 2018). "JAG1 is also highly expressed in medulloblastoma and colorectal cancer, and JAG1 causes poorer overall survival in breast cancer." (PMID 30231940, 2018). "Further, high levels of NOTCH and JAG1 were detected in tumors with poor-prognosis features and found associated with shorter survival compared to breast cancer patients with low tumor levels of NOTCH1 and JAG1." (PMID 27906684, 2017). "Previous studies demonstrated that high expression of JAG1 is frequently found in human breast cancer and is significantly associated with poor survival." (PMID 27029061, 2016). "JAG1 expression has been shown to be restricted to basal cells and its overexpression has been linked to basal-like breast cancer." (PMID 23863842, 2013). "Notch receptors are however, known to regulate cell fate determination, stem cell self-renewal, proliferation and apoptosis and JAG1 was previously associated with a poor prognosis for breast cancer patients." (PMID 22927939, 2012). "Expression of Notch1 and its ligand, JAG1, is associated with the poorest breast cancer survival and increased levels of VEGFR-2." (PMID 21731759, 2011). "Similarly, the activation of the Jag1/Notch1 pathway has been implicated as a key factor in the drug resistance of trastuzumab in breast cancer." (PMID 41315239, 2025). "Similarly, YAP1 has previously been linked to oncogenic phenotypes in breast cancer cells by acting at the upstream level of the Notch pathway and upregulating JAG1 expression." (PMID 36476410, 2022). "Jag1 is part of the notch signaling pathway involved in the renewal of stem and progenitor cells in mammary glands and has been associated with poor overall survival in breast cancer." (PMID 35087569, 2021). "Although elevated expression of the Jagged1 (Jag1) ligand is associated with both poor prognosis and bone metastasis in breast cancer patients, a detailed analysis of the functional role of Notch ligands in breast cancer initiation, growth and metastasis is still lacking." (PMID 30442981, 2019). "Therefore, the results suggest that the expressions of YAP1 and JAG1 are upregulated in breast cancer cells and they may be associated with advanced tumor grade and poor prognosis for breast cancers." (PMID 32046779, 2020).
breast carcinoma (continued). "Moreover, increased expression levels of JAG1 are associated with malignant progression and metastatic potential, recurrence and poor overall survival in multiple types of solid cancer such as prostate cancer, breast cancer, and gastric cancer." (PMID 29254197, 2017). "In another study, JAG1-positive fibroblasts were shown to interact with Notch3 in breast cancer cells to regulate resistance to chemotherapy." (PMID 39951484, 2025). "Knockdown of JAG1 in luminal breast cancer MCF-7 cells resulted in increased tumorsphere growth and cancer stem cell activity." (PMID 39890784, 2025). "In various cancers, including breast cancer, high JAG1 expression correlates with advanced features and poor survival." (PMID 38474093, 2024). "Knockdown of the JAG1 gene significantly reduced the potential for tumor organogenesis in triple-negative breast cancer (TNBC) cells, and JAG1-mediated adaptive resistance in Her2 breast cancer cells led to tumor recurrence." (PMID 38571938, 2024). "JAG1 is produced in the tumor microenvironment and an increase in its levels promotes breast cancer cells to transition into a more aggressive and invasive phenotype." (PMID 39408921, 2024). "ChIP-seq analysis reveals significant overlap between PML-, ER-, and Myc-bound promoters, suggesting their coordinated regulation of target gene expression, including genes involved in breast cancer stem cells (BCSCs), such as JAG1, KLF4, YAP1, SNAI1, and MYC." (PMID 37720048, 2023). "Previous studies have established this by demonstrating that JAG1 is highly expressed in metastatic prostate cancer and that high-level JAG1-NOTCH expression is observed in the angiogenesis of breast cancer." (PMID 37781534, 2023). "Our previous study has shown that KDM2A promotes angiogenesis, maintains cancer stemness, and induces drug resistance in breast cancer by regulating jagged-1(JAG-1) and SRY-box transcription factor 2 (SOX-2)." (PMID 37821959, 2023). "JAG1 acts as an oncogene in various cancers such as breast cancer, brain tumor, cervical cancer, colorectal cancer, and endometrial cancer." (PMID 35054034, 2022). "The siRNA against JAG1 reduced cyclin D1 expression and the inhibition of cell cycle progression via cyclin D1-dependent G1/S checkpoint-mediated proliferation in breast cancer cells." (PMID 36012128, 2022). "Endothelial JAG1 activates the Notch1 receptor on breast cancer cells to induce Zinc finger E-box-binding homeobox 1 (ZEB1) expression, which subsequently leads to the expression of stem cell markers." (PMID 35805056, 2022). "JAG1 was also highly expressed in grade I of breast cancer compared to other grades, and in grade, I compared to grade II, while DLL1 expression was higher in grade II and III than grade I." (PMID 36476410, 2022). "JAG1-NOTCH signaling between endocrine-resistant breast cancer cells and TAMs results in the differentiation of TAMs toward an M2-like phenotype, contributing to resistance to endocrine therapy." (PMID 35332121, 2022). "It has been reported that there is a positive association between the high expression of Jagged1 (JAG1) and the metastasis of breast cancer cells by initiating epithelial to mesenchymal transition EMT." (PMID 36476410, 2022). "Another recent study demonstrated that antibody-specific inhibition of JAG1 sensitizes chemoresistance of TNBC cells in vivo in mice, showcasing an important role for JAG1 and the Notch pathway in promoting chemoresistance in breast cancer." (PMID 35335125, 2022). "On the other hand, TCF7L2, ARRB1, DLL1, FZD7, HES1, and JAG1 transcript levels were significantly lower in breast cancer tissues than in normal samples (p < 0.0009, p = 0.0131, p = < 0.0001, p = < 0.0001, p = 0.0138, and p < 0.0001, respectively)." (PMID 36476410, 2022). "High JAG1 expression is correlated with bone-tropic metastatic breast cancer cell lines and samples from patient bone metastasised tumours." (PMID 34295896, 2021).
breast carcinoma (continued). "For instance, MIB1 has been shown to ubiquitinate JAG1 and activate Notch signaling in breast cancer." (PMID 33793053, 2021). "Knockdown of ZEB1 in breast cancer cells inhibits Notch activity, including downregulation of JAG1, MAML2/3 and HEY1 expression, via de-repression of miRNA-200 expression." (PMID 34295896, 2021). "During brain metastasis of breast cancer, cancer cells can secrete IL-1β to increase JAG1 expression in astrocytes and thus promote breast cancer stem cell renewal though the Notch signaling pathway." (PMID 34034721, 2021). "This RANK stimulation not only induces cell proliferation and survival but also induces the expression of JAG1 (upper half), which is likely to maintain breast cancer stem cells." (PMID 33840674, 2021). "JAG1 downregulation can induce cell cycle arrest to the G0 \G1 phase by regulating the binding of Notch and cyclin D1 promoter in breast cancer cells." (PMID 33795521, 2021). "In a single cell gene expression analysis, NOTCH4, NOTCH3 and JAG1 were upregulated in metastatic breast cancer cells compared to primary tumour cells isolated from TNBC patient-derived xenograft (PDX) models." (PMID 34295896, 2021). "For example, JAGGED1-Notch1-deployed tumor perivascular niches promote breast cancer stem cell phenotypes via Jag1-Notch1-Zeb1-VEGFA signal." (PMID 34725550, 2021). "Based on these results, we focused on Notch signaling and found that in various basal-like breast cancer cell lines, JAG1, a Notch ligand, was induced by NF-κB activation." (PMID 33840674, 2021). "JAG1-induced Notch signalling is also important in breast cancer cell colonisation of the bone metastatic niche." (PMID 34295896, 2021). "In hormone-therapy resistant breast cancers, tamoxifen can also enhance stemness via JAG1-NOTCH4 signaling." (PMID 34374886, 2021). "In clinical trials, patients with HER2-positive breast cancers with high JAG1 or NOTCH1 expression show low overall survival." (PMID 34374886, 2021). "JAG1 was first discovered in breast cancer patients, and high JAG1 expression implied significantly shorter overall survival." (PMID 33795521, 2021). "JAG1 has been considered as a tumorigenic gene in ovarian carcinoma, breast carcinoma, and multiple myeloma." (PMID 34421997, 2021). "For instance, in the context of breast cancer, the Notch ligand JAG1 correlates with lower overall survival and triple-negative breast cancer organoid formation in vitro, while EMT progression can be activated in a WNT/beta-catenin-dependent manner." (PMID 34830900, 2021). "Conversely, in clear cell renal cellular carcinoma and in breast cancer, DNA hypo-methylation of JAG1 partially mediated oncogenic hyper-activation of Notch signaling, favoring tumor progression." (PMID 34680255, 2021). "Jag1 derived from tumor cells can promote maturation of osteoclasts and osteolytic bone metastasis of breast cancer by regulating release of IL6 from osteoblasts." (PMID 34374886, 2021). "As a key ligand of Notch signaling pathway, high level of JAG1 was found in breast cancer, ovarian cancer and metastatic prostate cancer and was linked to poor survival rate." (PMID 33425722, 2020). "In this work, we highlight that targeting the angiocrine Jag1-Notch1-Zeb1-VEGFA loop decreases breast cancer aggressiveness and thus enhances the efficacy of antiangiogenic therapy." (PMID 33046710, 2020). "Transcription of JAG1 is elevated in mammary tumors and correlates with bad prognosis and low expectations of overall breast cancer survival." (PMID 32179814, 2020). "Overexpressed linc-OIP5, YAP1, and JAG1 were found in breast cancer cell lines MCF7 and MDA-MB-231 and the expression levels of YAP1 and JAG1 were proportional to the breast cancer tissue grades." (PMID 32046779, 2020). "Our study revealed a role for Jag1-Notch1-Zeb1-VEGFA-mediated angiocrine signaling in fostering tumor-initiating-cell niches in breast cancer." (PMID 33046710, 2020).